FGFR1 (fibroblast growth factor receptor 1)
Diseases named in the same sentence as FGFR1 in open-access papers (continued):
Sharing a sentence is not in itself a finding about the gene and the disease.
squamous cell lung carcinoma (continued). "For example, the increased gene copy number of FGFR1 is used as a biomarker to predict the response of squamous-cell lung cancer patients to FGFR tyrosine kinase inhibitor in clinical trials." (PMID 25226542, 2014). "So far, about 40% of lung squamous cell carcinoma has been found harbouring driver oncogenes, in which fibroblast growth factor receptor 1 (FGFR1) plays important roles." (PMID 24854563, 2014). "FGFR1 mutations are rarely observed in NSCLC, while FGFR1 amplification is frequent in, e.g., squamous cell lung carcinoma and associated with increased protein levels and a FGFR1 proliferation dependency." (PMID 24205279, 2013). "A single case report has shown that the FGFR inhibitor BGJ398 did demonstrate partial response in a patient with squamous cell lung carcinoma whose tumor was amplified for FGFR1." (PMID 24255716, 2013). "Ongoing trials are evaluating the role of FGFR inhibitors in tumors with FGFR1 activation, including squamous cell carcinoma of the lung." (PMID 24255716, 2013). "Growth dependence of these cell lines on FGFR1 amplification identifies this genetic variation as a high-frequency therapeutic target in squamous cell lung cancer." (PMID 23936763, 2013). "Based on SNP array copy number analysis of 732 samples, we report that FGFR1 is somatically amplified in 21% of lung squamous cell carcinomas as compared to 3.4% of lung adenocarcinomas." (PMID 21666749, 2011). "Using SNP array analysis, we found that a region of chromosome segment 8p11-12 containing three genes–WHSC1L1, LETM2, and FGFR1–is amplified in 3% of lung adenocarcinomas and 21% of squamous cell lung carcinomas." (PMID 21666749, 2011). "CD44/PAK1/AKT activation may help predict the response to FGFR1 inhibition in squamous cell lung cancer." (PMID 41459112, 2026). "In addition, FGFR1-mediated YAP upregulation initiates PD-L1 transcription in squamous cell lung cancer." (PMID 40362630, 2025). "Subsequent immune checkpoint analysis revealed that the high risk group had increased expression of CD44, a stemness marker of non-small cell lung cancer, and activation of CD44 related pathways promoted squamous cell lung cancer resistance to FGFR1 inhibition." (PMID 36814485, 2023). "The discovery of frequent 8p11-p12 amplifications in squamous cell lung cancer (SQLC) has fueled hopes that FGFR1, located inside this amplicon, might be a therapeutic target." (PMID 37606995, 2023). "PC9 is a human lung adenocarcinoma cell line with EGFRL858R mutation without FGFR1 expression, while H520 is a human lung squamous cell carcinoma cell line with the high expression of FGFR1 but without EGFR expression." (PMID 31998131, 2019). "It was also reported that MYC could enhance the oncogenic effect of FGFR1 in squamous cell lung cancer." (PMID 31695781, 2019). "In a phase Ib study in FGFR1 amplified squamous cell lung cancer, 15 patients received AZD4547." (PMID 35582593, 2019). "They showed, that increased SOX2 and FGFR1 gene copy number is a common event in squamous cell lung cancer patients and could demonstrate their improved overall survival." (PMID 29596469, 2018). "High FGFR1/CEN8 ratio has been used to screen patients of squamous cell lung cancer who may benefit from treatment with FGFR inhibitors." (PMID 29179482, 2017). "The cancers in which FGFR gene amplifications are most frequent include bladder urothelial carcinomas (FGFR1), squamous cell lung cancer (FGFR1), head and neck squamous cell cancer (FGFR1), uterine carcinosarcoma (FGFR3), breast adenocarcinoma (FGFR1), and gastric adenocarcinoma (FGFR2)." (PMID 26224133, 2015). "Finally, we were able to demonstrate a strong intrinsic variation of AKT phosphorylation by immunohistochemical staining of phosphorylated AKT in tissue samples from patients with squamous-cell lung-cancer characterized by either FGFR1 amplification (n = 33) or FGFR1 protein overexpression (n = 50)." (PMID 35853934, 2022).
squamous cell lung carcinoma (continued). "This apparent discrepancy in the frequencies of FGFR1 copy number gain may be a result of the different methodologies used in the studies, and/or the influence of biopsy samples from patients with metastatic squamous cell lung cancer." (PMID 25348872, 2014). "Amplification of FGFR1 as a biomarker supports the use of combined FGFR and MEK inhibitors in lung squamous cell carcinoma." (PMID 37941550, 2023). "THSD7A positivity predicts poor overall survival in female patients with squamous cell carcinoma of the lung and shows a relation to high FAK expression and FGFR1 wild type in this subgroup." (PMID 37445817, 2023). "Fibroblast growth factor receptor 1 (FGFR1) gene amplification is one of the most prominent and potentially targetable genetic alterations in squamous-cell lung cancer (SQCLC)." (PMID 35853934, 2022). "Squamous cell lung cancer and SCLC samples were hybridized with fluorescent probes against FGFR1 gene on chromosome 8 and amplification status was evaluated as described in materials and methods." (PMID 32207251, 2020). "Although EGFR L858R mutation was detected throughout the transformation, genomic analyses were performed during the disease course, revealing the amplification of FGFR1 and NSD3, which have recently been proposed as potential driver oncogenes in lung squamous cell carcinoma." (PMID 40792216, 2025). "FGFR1 amplification is not a reliable biomarker for FGFR inhibitors in treating lung squamous cell carcinoma due to its limited efficacy with only 7% to 11% of patients exhibiting durable responses in clinical trials." (PMID 37941550, 2023). "Ablation of NSD3, but not FGFR1, attenuated tumor growth in a mouse model of lung squamous cell carcinoma." (PMID 36360250, 2022). "As a negative control,we employed the squamous cell lung carcinoma HCC-15 cell line devoidof detectable FGFR1." (PMID 34855396, 2021). "FGFR1 amplification is also an independent negative prognostic factor in gastric cancer, lung squamous cell carcinoma and TNBC." (PMID 31987043, 2020). "Resulting conjugate shows high and specific cytotoxicity towards FGFR1-positive cells, i.e., squamous cell lung carcinoma NCI-H520, while remaining non-toxic for FGFR1-negative cells." (PMID 33076489, 2020). "In another study, FGFR1 amplification is an independent negative prognostic factor in surgically resected squamous cell lung cancer." (PMID 29088806, 2017). "Importantly, the data also demonstrated the potential activation of STAT3 by a number of upstream receptor tyrosine kinase signaling pathways found to be recurrently amplified in squamous cell lung carcinoma, including PDGFRA and/or KIT, EGFR, and FGFR1." (PMID 25573684, 2015). "FGF2 amplification rather than FGFR1 amplification may be the predominant mechanism for increased FGFR1 signalling as it correlated with higher PD-L1 expression in human lung squamous cell carcinoma and urothelial cancers." (PMID 40362630, 2025). "PeptibodyF2-MMAE, being peptibodyF2 conjugated with a cytotoxic drug, shows high and specific cytotoxicity towards cell lines expressing FGFR1, i.e., squamous cell lung carcinoma NCI-H520, while remaining non-toxic for cells with physiological FGFR1 levels." (PMID 33076489, 2020).
Kallmann syndrome (67 papers, 2009 to 2026). Kallmann syndrome (KS) is a developmental genetic disorder characterized by the association of congenital hypogonadotropic hypogonadism (CHH) due to gonadotropin-releasing hormone (GnRH) deficiency, and anosmia or hyposmia (with hypoplasia or aplasia of the olfactory bulbs). "FGFR1 variants were the most frequently detected and were commonly associated with anosmia and additional developmental anomalies." (PMID 41535479, 2026). "It has been reported that variants of FGFR1 cause Kallmann syndrome (KS), and variants have been detected in 10% of KS cases." (PMID 40141355, 2025). "Mutations of Anosmin 1 (KAL1) and Fibroblast Growth Factor Receptor 1 (FGFR1) lead to Kallmann syndrome, and mutations of the GNRHR and FSHR genes can result in isolated hypogonadotropic hypogonadism." (PMID 41465244, 2025). "In conclusion, we reported a case of KS discovered from signs and symptoms of hypogonadotropic hypogonadism and anosmia with a novel variant of FGFR1 (c.2197_2199dup, p.Met733dup)." (PMID 40141355, 2025). "Pathogenic variants in FGFR1 have been linked to phenotypically distinct disorders, including Hartsfield syndrome, Kallmann syndrome, Jackson–Weiss syndrome, osteoglophonic dysplasia, and Pfeiffer syndrome." (PMID 40428317, 2025). "The incidence of FGFR1 mutations in Kallmann syndrome is about 10%, and in the last decades many pathogenic mutations in associated genes including Spry4 have been identified in patients." (PMID 40806483, 2025). "This special derivative is derived from a mutation associated with Kallmann syndrome, a morphological disorder often caused primarily by genomic alteration resulting in reduced FGFR1 signalling." (PMID 40806483, 2025). "Striking pleiotropy, like those observed in FGFR1, was noted for selected pedigrees as patients harboring identical mutation presented various phenotypical spectrums of KS, nIHH, or isolated anosmia." (PMID 39010903, 2024). "Autosomal-dominant Kallmann syndrome, whose main features are anosmia and hypogonadism, is caused by loss-of-function mutations in FGFR1, and 5–10% of these patients have cleft." (PMID 37020525, 2023). "FGFR1 mutations are associated with delayed puberty, anosmia, cleft palate, mirror movements, dental agenesis, and bimanual synkinesia, although some familial cases have males and females with FGFR1 mutations who are asymptomatic carriers." (PMID 34231173, 2022). "FGF8 and FGFR1 deficiency is associated with Kallmann Syndrome (KS), a congenital disease characterized by hypogonadotropic hypogonadism and anosmia." (PMID 36619551, 2022). "The FGFR1 deletion is associated with Kallmann syndrome, hypogonadotropic hypogonadism with anosmia, or hypo-olfaction." (PMID 35668409, 2022). "The deletion of a short arm fragment on chromosome 8 is a rare cause of Kallmann syndrome and spherocytosis due to deletion of the FGFR1 and ANK1 genes." (PMID 35668409, 2022). "Kallmann syndrome caused by ANOS1 gene mutations is inherited by X-linked recessive trait as it is located on chromosome X. FGFR1 and PROK2/PROKR2 lead to autosomal dominantly inherited type of CHH." (PMID 32222824, 2021). "Pathogenic loss-of-function variants of the FGFR1 gene were reported to be involved in patients with Kallmann Syndrome, including hypogonadotropic hypogonadism and anosmia, and isolated HH." (PMID 34440300, 2021). "Pathogenic FGFR1 variants have been associated with Kallmann syndrome and hypogonadotropic hypogonadism." (PMID 34440300, 2021). "Many FGFR1 mutations have been identified in both Kallmann syndrome and isolated hypogonadotropic hypogonadism (IHH)." (PMID 34440300, 2021). "As in the case of FGFR1 mutations, there is wide phenotypic variability, ranging from KS through nCHH to isolated anosmia." (PMID 32508745, 2020). "Another FGFR1 missense variant c.1964 T > C (p.Leu655Pro) was identified in a female with KS referred to genetic counselling because of delayed puberty and anosmia." (PMID 31996231, 2020).
Kallmann syndrome (continued). "The function of FGFR1 in the normal development of the olfactory bulb proposes the link of anosmia with GnRH deficiency in the FGFR1-mutated patients." (PMID 32982993, 2020). "As anosmia has been associated with pathogenic variants in FGFR1 and KLB, the subjects underwent smell identification testing." (PMID 33210059, 2020). "Mutations in FGFR1 have previously been reported in patients with Kallmann syndrome; more recently, FGFR1 variants have been associated with CPHD, absent corpus callosum, SOD, and midline defects." (PMID 33634051, 2020). "Loss-of-function (LoF) mutations in FGFR1 cause familial and sporadic Kallman syndrome (KS) and normosmic idiopathic hypogonadotropic hypogonadism." (PMID 31652620, 2019). "In Kallmann Syndrome, which results in cleft palate, FGFR1 loss of function mutations have been identified in human populations and the FGFR-1c isoform is required for palate development." (PMID 28747655, 2017). "Loss-of-function mutations in FGFR1 gene cause variable HH phenotypes encompassing pubertal delay to idiopathic HH (IHH) or Kallmann syndrome (KS)." (PMID 28008864, 2017). "Kallmann syndrome (KS) patients carrying FGFR1 mutations can transmit the disorder to their offspring as can asymptomatic female carriers of mutations in KAL1." (PMID 26051373, 2015). "It is well known that FGFR1 mutations cause the Kallmann syndrome, a heterogeneous genetic disorder that associates HH due to GnRH deficiency with anosmia." (PMID 24489542, 2013). "Thus, the loss-of-function mutations in FGFR1 cause failed morphogenesis of the olfactory bulbs, leading to anosmia or hyposmia and CHH observed in patients with KS." (PMID 40428317, 2025). "Fibroblast growth factor receptor 1 (FGFR1), also known as KAL2, is a tyrosine kinase receptor, and variants of FGFR1 have been detected in patients with Kallmann syndrome (KS), which is a congenital developmental disorder characterized by central hypogonadism and anosmia." (PMID 40141355, 2025). "Pathogenic variants in ANOS1 and FGFR1 cause Kallmann’s syndrome." (PMID 35432193, 2022). "Mutations in FGFR1 (previously named KAL2) were first associated with Kallmann syndrome in 2003." (PMID 35457241, 2022). "FGFR1 loss-of-function mutations were also reported to be found in Kallmann syndrome patients with skeletal phenotypes, including oligodactyly, hemivertebrae and butterfly vertebrae and FGFR1 signaling was reported to be important for different stages of osteoblast maturation." (PMID 34440300, 2021). "Similarly, variants in FGFR1 and other HH genes have been shown to cause Kallman syndrome in an oligogenic manner." (PMID 34498060, 2021). "The FGFR1 mutations determining KS are characterized by incomplete penetrance and variable clinical expression of the same mutation in the same family, with patients displaying complete phenotype, only anosmia, or isolated pubertal delay." (PMID 32508745, 2020). "Additionally, there has been one case of Kallman syndrome in which the affected patient carried both a missense variant in FGFR1 (R78C) and a single amino acid deletion in KLB (F777delF)." (PMID 33210059, 2020). "Indeed, FGF8 and FGFR1 deficiency severely compromises vertebrate reproduction in mice and humans and is associated with Kallmann Syndrome (KS), a congenital disease characterized by hypogonadotropic hypogonadism associated with anosmia." (PMID 31361780, 2019). "Thus, CNVs containing such genes may not have clinical significance or may result in a completely different phenotype (e.g., mutations in FGFR1 lead to skeletal dysplasia while deletions are associated with Kallmann syndrome)." (PMID 34563047, 2021). "However, no unique phenotypic abnormalities were observed in that patient that could distinguish them from those seen in Kallmann Syndrome arising from FGFR1 point mutations." (PMID 23809228, 2013). "After sequencing, we found that 65 protein genes had been deleted, including FGFR1, which resulted in Kallmann syndrome." (PMID 35668409, 2022).
Kallmann syndrome (continued). "In this study, we present the clinical and genetic studies of two siblings affected with Kallmann Syndrome and normosmic CHH, respectively, leading to the identification of a novel missense mutation in the Fibroblast Growth Factor Receptor 1 (FGFR1) gene." (PMID 35457241, 2022). "In Kallmann syndrome, anosmia/hyposmia is part of the clinical picture, and ANOS1, CHD7, FGFR1, PROK2, PROKR2, and SEMA3A variants were reported to be involved in isolated congenital anosmia." (PMID 32222824, 2021). "Genetic mutations implicated in Kallmann syndrome (KS), such as KAL1, FGFR1, PROKR2, and FGF8, have also been recently identified in patients with SOD." (PMID 33634051, 2020). "According to these authors’ assessment, mutations in KAL1 appear in about 8% of cases of Kallmann syndrome, FGF8 and FGFR1 both appear in about 10% of cases and mutations both in PROKR2 or PROK2 are responsible for about 9% of cases." (PMID 32722328, 2020). "A tumor with a high level FGFR1 amp (C1037BL) and one with an FGFR1 R209H mutation (C1007BL), previously reported in Kallmann syndrome, had partial responses and prolonged benefit." (PMID 31287991, 2019). "In this publication, PMID 17154279, the authors report on the possible implication of the gene FGFR1 in the Kallmann syndrome." (PMID 29220432, 2017). "Mutations in KAL2, which encodes the fibroblast growth factor receptor FGFR1, leads to the autosomal dominant form of Kallmann syndrome." (PMID 26994098, 2016). "SNPs in genes involved with syndromes were previously associated with a variety of facial measurements, for example, genes such as FGFR1 (e.g., Pfeiffer syndrome and Kallmann syndrome), IRF6 (e.g., Van der Woude syndrome), and RUNX2 (e.g., cleidocranial dysplasia syndrome)." (PMID 40303982, 2025). "FGFR1 D129A has been reported by others in an individual with Kallmann syndrome which, in addition to its presence in our proband’s daughter, suggests that it may also contribute to congenital hypopituitarism." (PMID 40064730, 2025). "Phenotypically, affected individuals with Kallmann syndrome combined with FGFR1 variants are enriched with non-reproductive signs, most prevalent of which are skeletal anomalies of the hand or feet, dental agenesis and midline defects, namely cleft lip/palate." (PMID 40434549, 2025). "Thus far, FGFR1 and FGF8 gene variants have been identified to be causative genes not only for Kallmann syndrome, but also for CPHD, septo-optic dysplasia and holoprosencephaly." (PMID 35805171, 2022). "Therefore, anosmia, sexual dysplasia, irregular tooth alignment, cleft lip and palate, syndactyly, and renal abnormalities were common phenotypes of IHH patients with FGFR1 gene variants." (PMID 35090434, 2022). "However, the variants of FGFR1 and FGFR2 have been found in hypogonadotropic hypogonadism 2 with anosmia (rs121909642), Pfeiffer syndrome, craniosynostosis syndrome (rs121918506), and in LADD syndrome (rs121918509), respectively." (PMID 34714320, 2021). "Some mutations in FGFR1 affect the sense of smell while others do not, resulting in Kallmann syndrome (KS) and normosmic isolated hypogonadotropic hypogonadism (nIHH), respectively." (PMID 33299522, 2020). "Pathogenic variants in FGFR1 and KLB have individually been described in the setting of Kallman syndrome, a disorder characterized by hypogonadotropic hypogonadism and loss of smell (anosmia)." (PMID 33210059, 2020). "FGFR1 mutations are also associated with increased risk of nonsyndromic CL/P, as well as of Kallmann syndrome with CL/P and Hartsfield syndrome, which is characterized by holoprosencephaly, ectrodactyly, and CL/P." (PMID 31122291, 2019). "Moreover, mutations in FGFR1 and FGFR2 genes have been established in the pathogenesis of some syndromes in which clefts are present, such as Apert syndrome (FGFR2), Crouzon syndrome (FGFR2, FGFR3), Hartsfield syndrome (FGFR1) and Kallmann syndrome (FGFR1, FGF8)." (PMID 35455561, 2022).